NLGN1 (neuroligin 1)
Description:
Cell surface protein involved in cell-cell-interactions via its interactions with neurexin family members. Plays a role in synapse function and synaptic signal transmission, and probably mediates its effects by recruiting and clustering other synaptic proteins. May promote the initial formation of synapses, but is not essential for this. In vitro, triggers the de novo formation of presynaptic structures. May be involved in specification of excitatory synapses. Required to maintain wakefulness quality and normal synchrony of cerebral cortex activity during wakefulness and sleep (By similarity). The protein is involved in nervous system development.
Synonyms: KIAA1070; NLG1; NL1
Tractability: Small molecule: it belongs to a druggable protein family. Antibody: UniProt places it where antibodies can reach, with high confidence; its Gene Ontology location is reachable by antibodies, with high confidence; UniProt predicts a signal peptide or a membrane-spanning region. PROTAC: ubiquitination databases record sites on it; its protein half-life has been measured.
Gene: Protein-coding gene on chromosome 3 (173,396,284 to 174,294,372, forward strand). Ensembl gene ENSG00000169760.
Subcellular location: Cell membrane; Postsynaptic density; Synaptic cleft; Synaptic cell membrane; Cell projection, dendrite; Synapse
Subcellular location (Human Protein Atlas): Plasma membrane; Nuclear bodies
Pathways (Reactome):
Neuronal System: Neurexins and neuroligins
Gene Ontology:
Molecular function: PDZ domain binding; scaffold protein binding; amyloid-beta binding; cell adhesion mediator activity; cell adhesion molecule binding; identical protein binding; neurexin family protein binding; signaling receptor activity
Biological process: negative regulation of dendritic spine morphogenesis; nervous system development; neuron projection development; NMDA glutamate receptor clustering; positive regulation of dendritic spine development; positive regulation of excitatory postsynaptic potential; positive regulation of synapse assembly; AMPA glutamate receptor clustering; AMPA selective glutamate receptor signaling pathway; calcium-dependent cell-cell adhesion; cellular response to calcium ion; cytoskeletal matrix organization at active zone; establishment of protein localization; excitatory synapse assembly; heterophilic cell-cell adhesion; modulation of chemical synaptic transmission; neurexin clustering involved in presynaptic membrane assembly; neuron cell-cell adhesion; neuron projection arborization; neuron projection morphogenesis; neuronal signal transduction; NMDA selective glutamate receptor signaling pathway; positive regulation of circadian sleep/wake cycle, wakefulness; positive regulation of filopodium assembly; positive regulation of intracellular signal transduction; and 17 more
Cellular component: plasma membrane; asymmetric, glutamatergic, excitatory synapse; cell surface; dendrite; dendritic spine; excitatory synapse; filopodium tip; GABA-ergic synapse; glutamatergic synapse; Golgi apparatus; membrane; neuromuscular junction; postsynapse; postsynaptic density; postsynaptic membrane; postsynaptic specialization membrane; protein complex involved in cell-cell adhesion; receptor complex; synapse; synaptic cleft; synaptic membrane; neuron to neuron synapse; presynapse
Genetic constraint (gnomAD): Loss-of-function variants: 12 observed, 66.83 expected, observed/expected ratio (o/e) 0.18, 90% interval 0.11 to 0.29. The upper end of that interval is the gene's LOEUF score, 0.29, which puts it in group 1 of 6, group 1 being the genes least tolerant of losing a copy. Missense variants: 746 observed, 1,046.6 expected, observed/expected ratio (o/e) 0.71, 90% interval 0.67 to 0.76. Synonymous variants: 347 observed, 372.57 expected, observed/expected ratio (o/e) 0.93, 90% interval 0.85 to 1.02.
Homologues: Orthologues: chimpanzee NLGN1 (98% identical), rat Nlgn1 (97% identical), macaque NLGN1 (97% identical), pig NLGN1 (97% identical), dog NLGN1 (97% identical), guinea pig NLGN1 (96% identical), rabbit NLGN1 (96% identical), mouse Nlgn1 (96% identical), tropical clawed frog nlgn1 (88% identical), zebrafish nlgn1 (83% identical), Drosophila melanogaster Jhe (19% identical), Caenorhabditis elegans cest-27 (18% identical), and 40 more. Paralogues in human: NLGN4X (70% identical), NLGN4Y (70% identical), NLGN3 (69% identical), NLGN2 (62% identical), CES3 (23% identical), CES5A (23% identical), CES2 (23% identical), CES1 (22% identical), CES4A (22% identical), BCHE (22% identical), ACHE (21% identical), CEL (21% identical), and 1 more.
Diseases named in the same sentence as NLGN1 in open-access papers:
NLGN1 is named in the same sentence as 68 diseases in open-access papers, as found by Europe PMC text mining. Sharing a sentence is not in itself a finding about the gene and the disease. The quoted sentences say what the papers report.
autism (39 papers, 2011 to 2025). Persistent deficits in social interaction and communication and interaction as well as a markedly restricted repertoire of activity and interest as well as repetitive patterns of behavior. "Together, these findings suggest a restricted pattern of association of a mutant beta-Nrxn1 with glutamatergic Nlgn1 in a mouse model of autism, which initiates early after expression and is maintained throughout adulthood." (PMID 40087687, 2025). "In this study, we analysed the trans-synaptic interactions of alpha- and beta-Nrxn1 isoforms with Nlgn1 and Nlgn2 in cultured neurons and studied the type of association affected by mutant beta-Nrxn1 in a mouse model of autism." (PMID 40087687, 2025). "As possible targets we chose long genes which are associated with autism, namely Nrxn1, Nlgn1, contactin-associated protein 2 (Cntnap2) and discs large MAGUK scaffold protein 2 (Dlg2)." (PMID 36768419, 2023). "A number of these down-regulated long genes are associated with autism, including Nrxn1 and Nlgn1, which contribute to the regulation of synaptic functions." (PMID 36768419, 2023). "In cultured neurons, L1 siRNA reduces the expression levels of the long autism genes neurexin-1 (Nrxn1) and neuroligin-1 (Nlgn1) and of the mitochondrially encoded gene NADH:ubiquinone oxidoreductase core subunit 2 (ND2)." (PMID 36768419, 2023). "In this study, we provided evidence that DSCAM serves as a repressor for the NLGN1-NRXN1β interaction, and that its deficiency leads to premature spine maturation and excessive glutamatergic transmission, inducing autism-like behaviors." (PMID 34848499, 2022). "In DSCAM-deficient mice, this inhibition of the NLGN1-NRXN1β interaction was removed, and resulted in premature spine maturation, which ultimately led to autism-like behaviors and enhanced spatial memory." (PMID 34848499, 2022). "An example of a potential connection is described here between cadherin-8 and neuroligin-1, another autism risk candidate molecule." (PMID 34135003, 2021). "Currently, diseases associated with NLGN1 in previous studies include autism, post-traumatic stress disorder and schizophrenia." (PMID 34340665, 2021). "Several NLGN1 missense variants were found in autism patients and were demonstrated to be functionally significant in mice model." (PMID 34340665, 2021). "A1 splice inclusion in the autism-linked NLGN1 P89L mutant enhances presynaptic differentiation in coculture." (PMID 32915137, 2020). "NLGN1 has previously been associated with autism, and it encodes neuroligin 1, a protein involved in synaptogenesis, learning, and memory." (PMID 27219346, 2016). "The NLGN1 gene was previously reported to have significant association with other psychiatric disorders such as autism and major recurrent depression, which share some clinical symptoms with schizophrenia." (PMID 26674772, 2015). "To examine the protein level of the RNAseq results in mouse CAD cells, we tested genes involved in autism risk (NLGN1), neurodegeneration (ATXN1), neurogenesis (REST), embryonic development (TLE4), and neuronal migration (KIF1A)." (PMID 26094033, 2015). "Variants within the NLGN1 gene and alterations of the Neuroligin 1 synaptic pathway are reported to be involved in the etiopathogenesis of autism, neurodevelopmental disorders, memory loss, and depression, thus highlighting this gene’s relevance in brain function." (PMID 38397906, 2024). "We previously showed that the autism-related pathogenic effects of exaggerated cap-dependent translation on mouse brain physiology and behavior can be reversed by targeting “eIF4E-sensitive” mRNAs such as Nlgn1." (PMID 37293130, 2023). "The researchers found that neuroligin-1 knockout mice exhibited increased repetitive grooming movements similar to those observed in individuals with autism, suggesting that such repetitive movements may be associated with autism." (PMID 36088343, 2022).
autism (continued). "Modelling in Nlgn1 P89L heterozygous knock-in mice resulted in reduced NLGN1 protein levels and deficits in social interaction, altered social dominance, and impaired spatial memory, supporting a causative role of this mutation in autism." (PMID 32915137, 2020). "We propose that the A1 insert could be a target for alleviating the consequences of deleterious NLGN1/3 mutations, supported by assays with the autism-linked neuroligin-1-P89L mutant." (PMID 32915137, 2020). "Finally, several researches have indicated NLGN1 was significant associated with a variety of psychiatric phenotypes including autism and major recurrent depression." (PMID 26674772, 2015). "Moreover, a family-based association analysis of 100 families with autism found a modest significant association at a region in NLGN1 gene." (PMID 23697635, 2013). "NLGN1 variants may result in autism and Asperger’s syndrome." (PMID 35309141, 2022). "The fact that alpha-Nrxn1 isoforms do not participate in the glutamatergic differentiation mediated by Nlgn1 suggested an unshared mechanism for beta-Nrxn1 dysfunction in a mouse model of autism." (PMID 40087687, 2025). "Other variants (SNVs and CNVs) in NLGN1 and/or other family members NLGN3 and NLGN4 were previously associated with PTSD, autism, obsessive-compulsive disorder, and depression." (PMID 36253440, 2023). "We previously demonstrated that exaggerated cap-dependent translation leads to autism-related phenotypes and increased mRNA translation and protein expression of Neuroligin 1 (Nlgn1) in mice." (PMID 37293130, 2023). "Altogether, we reveal rescue of autism-related phenotypes in a mouse model of TSC by targeting Nlgn1, a key downstream effector molecule regulated by the mTORC1/4E-BP axis." (PMID 37293130, 2023). "Reduction of L1 levels by siRNA downregulated the expression levels of the long autism genes Nrxn1 and Nlgn1 and of the mitochondrial gene ND2." (PMID 36768419, 2023). "In the context of the present study, we would like to mention that L1-70 interacts with topoisomerase 1 and disruption of this interaction leads to changes in expression of the long autism genes neurexin 1 (Nrxn1) and neuroligin 1 (Nlgn1)." (PMID 37238646, 2023). "Other variants (SNVs and CNVs) in NLGN1 and/or other family members NLGN3 and NLGN4 were previously associated with suicide, PTSD, autism, obsessive–compulsive disorder (OCD), and depression." (PMID 36319817, 2022). "Variants in neuroligin 1 and SHANK2 have been implicated in susceptibility to autism, while variants in neuroligin 3 have been implicated in Asperger syndrome and autism." (PMID 34610269, 2021). "Intriguingly, a similar dysfunctional phenotype correlating with misfolding has been reported for the P89L variant of NLGN1 and the R215H variant of NLGN2, which are associated with autism and schizophrenia, respectively." (PMID 32873342, 2020). "The choice of D-cycloserine was informed by previous findings that this compound showed preclinical benefits in Neuroligin 1 KO mice (human autism and mental retardation) and Tourette syndrome with accompanying ADHD and/or OCD." (PMID 26637193, 2015). "Interestingly, we found that a mutant beta-Nrxn1 shows ligand restriction for glutamatergic Nlgn1 in the brain of a mouse model of autism." (PMID 40087687, 2025). "Importantly, the analysis of protein complexes associated with mutant beta-Nrxn1 suggested a selective dysfunction of the beta-Nrxn1/Nlgn1 pathway in a mouse model of autism." (PMID 40087687, 2025). "Together, these results suggest that NLGN1 is important in cognitive and repetitive behaviors characteristic of autism although the relationship between LTP, NMDA receptor-mediated synaptic transmission, and the observed behavioral deficits remains unclear." (PMID 27047540, 2016). "Interestingly, a CNV region in the NLGN1 gene was significantly enriched in individuals with autism." (PMID 23697635, 2013).
autism (continued). "Neuroligins (NLGN1–3, 4X, 4Y) are a family of post-synaptic cell adhesion molecules that are ligands of their trans-synaptic partner NRXN." (PMID 27047540, 2016). "Exonic CNVs of NLGN1 and DPP6 have been identified in individuals with autism." (PMID 27777633, 2016).
schizophrenia (12 papers, 2011 to 2025). A major psychotic disorder characterized by abnormalities in the perception or expression of reality. "For instance, NLGN1 polymorphisms were proved to be associated with schizophrenia in Chinese Han population." (PMID 34340665, 2021). "The results of gene expression analysis further supported the potential role of NLGN1 in brain function and schizophrenia susceptibility." (PMID 26674772, 2015). "In a recent Psychiatric GWAS Consortium (PGC) meta-analysis of schizophrenia GWAS (36,989 cases and 113,075 controls), there were several SNPs in the NLGN1 polymorphism that also showed moderate association with schizophrenia." (PMID 26674772, 2015). "Our study showed that seven SNPs of NLGN1 and two haplotype blocks were significantly associated with schizophrenia." (PMID 26674772, 2015). "Then, to corroborate the association between the NLGN1 gene and schizophrenia in the Chinese Han population, we performed an independent replication study in 1814 schizophrenia cases and 1487 healthy controls." (PMID 26674772, 2015). "In gene-level, the NLGN1 gene was also significant associated with schizophrenia in our dataset (P = 5.6×10−3) and PGC dataset (P = 6.72×10−4)." (PMID 26674772, 2015). "To further validate the association of NLGN1 in Chinese Han population, we selected eight most significant SNPs (P<0.01) of NLGN1 gene in our previous GWAS to validate in 1,814 schizophrenia cases and 1,457 healthy controls." (PMID 26674772, 2015). "Recently, we carried out a GWAS of schizophrenia in the Chinese Han population and found several novel candidate genes associated with schizophrenia, including the NLGN1 gene." (PMID 26674772, 2015). "First, several SNPs in NLGN1 were identified to be associated with schizophrenia in an independent sample." (PMID 26674772, 2015). "To explore the association between NLGN1 and schizophrenia, we extracted the SNP data of NLGN1 from our previous GWAS and the public PGC schizophrenia GWAS, which included 35,476 schizophrenia cases and 46,839 controls." (PMID 26674772, 2015). "Furthermore, the results indicated that NLGN1 was associated with schizophrenia in Chinese Han Populations." (PMID 26674772, 2015). "Additionally, in current study, several lines of evidences were also provided to support NLGN1 as a schizophrenia susceptibility gene." (PMID 26674772, 2015). "The results of SNP and gene level from these two GWAS suggested that NLGN1 might be associated with schizophrenia." (PMID 26674772, 2015). "Here we examined whether the CAMs pathway and NLGN1 contributed to schizophrenia susceptibility in Chinese Han population." (PMID 26674772, 2015). "This suggested that higher expression of NLGN1 in brain might be associated with schizophrenia." (PMID 26674772, 2015). "Based on our previous GWAS and PGC schizophrenia meta-analysis, we selected only one promising gene NLGN1 to validate in independent samples." (PMID 26674772, 2015). "To test the biological plausibility of NLGN1 in the pathogenesis of schizophrenia, we investigated expression enrichment profiling of the NLGN1 gene in multiple human tissues." (PMID 26674772, 2015). "Human Brain temporal-spatial expression analysis of NLGN1 also supported the potential role of NLGN1 in schizophrenia." (PMID 26674772, 2015). "Then, we selected one promising gene neuroligin 1 (NLGN1) to further investigate the association between eight significant SNPs and schizophrenia in an independent sample (1814 schizophrenia cases and 1487 healthy controls)." (PMID 26674772, 2015). "We also performed a meta-analysis using this replication sample and the first-stage GWAS sample and further investigate the relationship between NLGN1 and schizophrenia in silico analysis." (PMID 26674772, 2015). "Taken together, these evidences supported that the gene NLGN1 has a potential role in pathogenesis of schizophrenia." (PMID 26674772, 2015).
schizophrenia (continued). "Lines of genetic evidence and functional studies make NLGN1 a more promising candidate gene of schizophrenia." (PMID 26674772, 2015). "Copy number, truncating, and missense variants in NLGN1 are associated with autism spectrum disorders (ASD) and obsessive-compulsive disorder and NLGN1 polymorphisms are linked to schizophrenia." (PMID 32915137, 2020). "However, to our knowledge, the role of NLGN1 for schizophrenia was rarely known." (PMID 26674772, 2015).
Anxiety (11 papers, 2016 to 2025). Intense feelings of nervousness, tension, or panic often arise in response to interpersonal stresses. "Our in vivo data demonstrated that FGF2 restoration recover neuroligin 1-dependent glutamatergic synaptogenesis, inhibiting the progression of spatial memory loss, anxiety, and depressive mood." (PMID 35562616, 2022). "Also, neuroligin 1 genotype variations are associated with different levels of anxiety and fear in patients, suggesting a role of neuroligin 1 in emotional regulation." (PMID 34882968, 2022). "Thus, the reduced expression of Nrxn1 and Nlgn1 in mutant mice could contribute to the changes in anxiety and activity, as we report here." (PMID 37238646, 2023). "Moreover, pretreatment of FGF2 elevated neuroligin 1 expression and trafficking of GluR1/2 into the postsynaptic compartment of mice exposed to prenatal corticosterone, improving spatial memory and depression/anxiety-like behaviors." (PMID 35562616, 2022). "Inhibiting NLGN1 in D2‐MSNs did not affect the mice's movement distance, speed, anxiety levels, or social abilities." (PMID 39661696, 2025). "Our previous research has indicated that mice lacking NLGN1 display anxiety and deficits in social memory." (PMID 39661696, 2025). "Previous work indicated mice lacking Nlgn1 showed no changes across numerous behavioural measures including anxiety-like behaviours in the elevated plus maze, but displayed impaired spatial learning and memory in the Morris water maze." (PMID 34690694, 2021). "Although the Nlgn1 P89L heterozygous mice showed only a 30% reduction of NLGN1 protein in their brain, they displayed aberrant behavior, such as deficits in social interaction, altered social dominance and impaired spatial memory, without affecting basal locomotor activity and anxiety." (PMID 28841651, 2017).
autism spectrum disorder (10 papers, 2011 to 2022). A spectrum of developmental disorders that includes autism, and Asperger syndrome. "and neuroligin 1 (NLGN1), whose mutations are found to associate with various neurological diseases, including autism spectrum disorders." (PMID 29755516, 2018). "Human mutations in the neuroligin gene family have been repeatedly documented in neurodevelopmental disorders, including several NLGN1 variants identified in autism spectrum disorders, of which the majority are loss-of-function mutations reducing Nlgn1 expression." (PMID 34690694, 2021). "Finally, human mutations in NLGN genes, including NLGN1, have been reported in neurodevelopmental disorders including autism spectrum disorder." (PMID 32921313, 2020).